STAT6 (signal transducer and activator of transcription 6)
Description:
Carries out a dual function: signal transduction and activation of transcription. Involved in IL4/interleukin-4- and IL3/interleukin-3-mediated signaling.
Synonyms: D12S1644; IL-4-STAT; HIES6; STAT6B; STAT6C
Tractability: Small molecule: a structure with a bound ligand is known; a high-quality ligand is known; it belongs to a druggable protein family. PROTAC: ubiquitination databases record sites on it; its protein half-life has been measured; a small molecule that binds it is known.
Target class: Transcription factor
Gene: Protein-coding gene on chromosome 12 (57,095,404 to 57,132,139, reverse strand). Ensembl gene ENSG00000166888.
Subcellular location: Cytoplasm; Nucleus
Subcellular location (Human Protein Atlas): Cytosol; Nucleoplasm; Connecting piece
Pathways (Reactome):
Immune System: Interleukin-4 and Interleukin-13 signaling; STAT6-mediated induction of chemokines
Developmental Biology: Differentiation of naive CD4+ T cells to T helper 2 cells (Th2 cells)
Signal Transduction: Downstream signal transduction
Gene Ontology:
Molecular function: DNA-binding transcription activator activity, RNA polymerase II-specific; DNA-binding transcription factor activity; DNA-binding transcription factor activity, RNA polymerase II-specific; identical protein binding; protein binding; protein phosphatase binding; RNA polymerase II transcription regulatory region sequence-specific DNA binding; transcription coactivator binding; RNA polymerase II cis-regulatory region sequence-specific DNA binding; DNA binding; sequence-specific DNA binding
Biological process: cell surface receptor signaling pathway via JAK-STAT; cytokine-mediated signaling pathway; interleukin-13-mediated signaling pathway; interleukin-4-mediated signaling pathway; positive regulation of transcription by RNA polymerase II; defense response; growth hormone receptor signaling pathway via JAK-STAT; positive regulation of cold-induced thermogenesis; regulation of cell population proliferation; regulation of transcription by RNA polymerase II; response to peptide hormone; gene expression; regulation of DNA-templated transcription; signal transduction
Cellular component: cytosol; nucleoplasm; nucleus; RNA polymerase II transcription regulator complex; chromatin; cytoplasm
Genetic constraint (gnomAD): Loss-of-function variants: 43 observed, 107.6 expected, observed/expected ratio (o/e) 0.4, 90% interval 0.31 to 0.51. The upper end of that interval is the gene's LOEUF score, 0.51, which puts it in group 2 of 6, group 1 being the genes least tolerant of losing a copy. Missense variants: 797 observed, 1,101.4 expected, observed/expected ratio (o/e) 0.72, 90% interval 0.68 to 0.77. Synonymous variants: 411 observed, 430 expected, observed/expected ratio (o/e) 0.96, 90% interval 0.88 to 1.04.
Gene-disease validity (ClinGen):
ClinGen rates the evidence that STAT6 causes each of these diseases.
hyper-IgE syndrome 6, autosomal dominant, with recurrent infections (autosomal dominant): Strong.
Homologues: Orthologues: chimpanzee STAT6 (99% identical), macaque STAT6 (95% identical), pig STAT6 (93% identical), dog STAT6 (91% identical), guinea pig STAT6 (89% identical), rabbit STAT6 (88% identical), rat Stat6 (86% identical), mouse Stat6 (85% identical), tropical clawed frog stat6 (42% identical), zebrafish stat6 (33% identical), Drosophila melanogaster Stat92E (27% identical). Paralogues in human: STAT5A (34% identical), STAT5B (34% identical), STAT1 (22% identical), STAT3 (22% identical), STAT4 (22% identical), STAT2 (21% identical).
Diseases named in the same sentence as STAT6 in open-access papers:
STAT6 is named in the same sentence as 396 diseases in open-access papers, as found by Europe PMC text mining. Sharing a sentence is not in itself a finding about the gene and the disease. The quoted sentences say what the papers report.
asthma (129 papers, 2006 to 2026). "In humans, STAT6 is associated with asthma and other allergic diseases, as patients with a gain of function mutation in Stat6 showed a variety of allergic diseases, including asthma." (PMID 40276331, 2025). "This is consistent with our and previous observation of the association between this STAT6 variant and asthma." (PMID 37430141, 2023). "This stems from the fact that asthma is associated with enhanced IL-4-associated STAT6 phosphorylation and subsequent production of Th2 cytokines." (PMID 36348405, 2022). "STAT6 phosphorylation was associated with the capacity of Treg-of-B cells to alleviate inflammation in an animal model of asthma in vivo." (PMID 33919941, 2021). "Mice deficient for IL-4, IL-13, or STAT6 develop attenuation of certain features of asthma, including eosinophil recruitment and airway hyperresponsiveness." (PMID 30147700, 2018). "These asthma-associated genes were enriched for targets of STAT6 signaling, and they were nested within a larger coexpression module comprising 406 genes." (PMID 26922672, 2016). "Bioinformatics analyses showed that these asthma-associated genes were enriched with targets of STAT6 signaling." (PMID 26922672, 2016). "Several transcription factors have also been implicated in the inflammatory process of asthma, including STAT6 and NF-κB." (PMID 26075216, 2015). "Genomewide association studies have revealed that special polymorphism haplotype variants and epigenetic modifications of STAT6 are associated with asthma in childhood." (PMID 24790987, 2014). "In conclusion, our present study reported for the first time a comprehensive meta-analysis to determine the association between the STAT6 gene polymorphisms and the risk of asthma based on data published until December 8, 2012." (PMID 23861779, 2013). "Given that the frequencies of GT14 and GT16 alleles were extremely lower than those of GT13 and GT15 alleles, we considered GT13 and GT15 as the most dominant risk alleles of asthma for STAT6 GT repeat polymorphism." (PMID 23861779, 2013). "Six articles presenting seven studies have demonstrated the association between the STAT6 G2964A polymorphism and susceptibility to asthma." (PMID 23861779, 2013). "The present meta-analysis considered 12 case-control studies in 11 articles and was the first meta-analysis report to investigate the association between the two common polymorphisms in STAT6 and the susceptibility to asthma." (PMID 23861779, 2013). "A total of five studies describing the association between the STAT6 GT polymorphism and the risk of asthma were enrolled in the meta-analysis." (PMID 23861779, 2013). "Studies have reported the association between STAT6 gene polymorphisms and the susceptibility to asthma in various populations." (PMID 23861779, 2013). "Though STAT6 is primarily known to be associated with allergic inflammation and asthma, STAT6 deregulation has also been implicated in various other diseases." (PMID 22162773, 2011). "In order to track the exogenous in vivo primed T cells that we were transferring into these mice and to prevent interference of TH1 cells, we used STAT6 or IL-4Rα deficient mice on a RAG2-/- background for our asthma experiments." (PMID 22014099, 2011). "This IL-4 induction was found to be dependent on expression of STAT6, a transcription factor strongly implicated in chronic Th2 pathologies including asthma." (PMID 17134490, 2006). "The STAT6 rs324011 variant may increase asthma risk because STAT6 mediates the biological effects of a cytokine necessary for type 2 differentiation of T cells and B-cell survival, proliferation, and class switching to IgE." (PMID 40375219, 2025). "The TT genotype and T allele of the STAT6 rs324011 polymorphism may be associated with increased susceptibility to pediatric asthma among Yemeni children." (PMID 40375219, 2025).
asthma (continued). "Indeed, STAT6 is known to participate in IL-4 signaling and its role in asthma has been extensively studied since both doctor-diagnosed asthma and blood eosinophil counts are known to be linked to STAT6 signaling and the IL-1 receptor family." (PMID 38773393, 2024). "In support of a role for genetic variation in STAT6 in human allergic disease, many single nucleotide polymorphisms (SNP) of STAT6 are associated with atopic disorders, including atopic dermatitis, eczema herpeticum, food allergies, eosinophilic esophagitis and asthma." (PMID 37316763, 2023). "The STAT6 signaling pathway might be involved in the pathogenesis of asthma development associated with AD." (PMID 35177102, 2022). "AS1517499 could partially block the association between AD and asthma by specifically inhibiting the STAT6 signaling pathway." (PMID 35177102, 2022). "Additionally, variants of STAT6 were closely associated with asthma risk, and deficiency of STAT6 affects immune function, glycolysis, and B cell morphology, which contributes to various diseases." (PMID 36324680, 2022). "Accordingly, rs167769 is strongly associated with STAT6 expression in the blood and lungs and is associated with increased risk of childhood atopic dermatitis, which often progresses to allergic airways diseases such as asthma in adulthood." (PMID 34669738, 2021). "Our results show, for the first time, that such anti-asthma effects may be associated with reduction of the IL-4/JAK1/STAT6 pathway." (PMID 30172259, 2018). "STAT6 gene is located at 12q13.314.1, one of the most susceptible regions associated with asthma." (PMID 23861779, 2013). "For the GT dinucleotide repeat length polymorphism in exon 1 of STAT6, the S allele (≤14 repeats) and the L allele (≥15 repeats) were compared, suggested a significantly strong association between the S allele and the susceptibility to asthma." (PMID 23861779, 2013). "Various studies have investigated the STAT6 GT repeat polymorphism and the risk of asthma." (PMID 23861779, 2013). "However, none of these GWA studies revealed any association of the variants in STAT6 gene with asthma." (PMID 23861779, 2013). "Polymorphisms in the Il4ra and Stat6 genes have been linked to increased risk of asthma." (PMID 22014099, 2011). "However, it has to be considered that there are only very few genes that have been associated in the first place to IgE such as STAT6, whereas most reported candidate genes for total IgE were investigated in asthma or eczema cohorts." (PMID 18846228, 2008). "Furthermore, earlier studies have revealed an IL-4/STAT-6/Tfec/IL-4Rα positive feedback regulatory loop, in which Tfec transcribes IL-4Rα expression to promote M2 programming in macrophages, which was implicated in asthma pathogenesis." (PMID 35600600, 2022). "STAT6 polymorphisms on locus 12q13, previously associated with serum IgE levels, allergic sensitization, and asthma, have also been reported to have a major genetic association in EoE independent of sensitization but a subsequent meta-analysis did not confirm the finding." (PMID 35095572, 2021). "Indeed, IL-13, an inflammatory cytokine highly associated with asthma induced activation of STAT6 has been shown to increase mucin expression and mucus metaplasia in both airway epithelial cells and submucosal glands in mice and has been linked to goblet cell hyper/metaplasia in humans." (PMID 35386986, 2021). "We hypothesized that interactions between genetic variants and methylation in genes in this pathway (IL4, IL4R, IL13, GATA3, and STAT6) influence asthma risk, that such influences are age-dependent, and that methylation of some CpG sites changes over time in accordance with asthma transition." (PMID 24735657, 2014). "Our published data indicate that topical administration of an immunomodulatory peptide, STAT6-IP, at the time of antigen priming inhibits T helper 2 adaptive immunity in murine models of asthma, at least in part, through inhibition of dendritic cells (DCs)." (PMID 41904701, 2026).
asthma (continued). "The consistency of these findings across genetically and environmentally distinct populations underscores the potential universality of STAT6’s role in asthma pathogenesis, particularly in IgE-mediated pathways." (PMID 40375219, 2025). "For instance, STAT6-immunomodulatory peptides have been shown to reduce type 2 innate lung inflammation and Th2 adaptive immunity, suggesting potential for reducing asthma symptoms." (PMID 40375219, 2025). "Asthma, atopic dermatitis in case of hyper-activation STAT6 and Th2 deficit in case of downregulation of STAT6." (PMID 39859036, 2025). "A chimeric decoy ODN, which inhibits both NF-κB and the allergic mediator signal transducer and activator of transcription 6 (STAT6), was also developed and used in a mouse model for asthma." (PMID 38247922, 2024). "We also found an ir-QTL (rs703816) for an isoform of STAT6 (STAT6_1) that co-localized with the asthma signal." (PMID 39288763, 2024). "STAT6 activation mediates the classic Th2-high asthma response, whereas p38 MAPK activation is usually related to severe Th2-low asthma." (PMID 37048067, 2023). "STAT6 plays clear mechanistic roles in allergy and asthma, and a recent study showed that altered STAT6 expression due to rare germline gain of function promoter mutations cause severe allergic disorders." (PMID 38062486, 2023). "Asthma-related transcription factors that are activated by PKCθ include STAT6, NFAT, GATA3, and nuclear factor kappa B (NF-κB)." (PMID 37569348, 2023). "STAT6 hyperactivation in airway epithelial cells and resident dendritic cells can further create an environment favoring asthma and chronic lung disease, as this would induce production of chemokines that promote TH2 cells and eosinophil recruitment." (PMID 36884218, 2023). "In summary, we found that BGE exerts anti-inflammatory activity both in vitro and in vivo by reducing the activation of PKCθ and asthma-associated transcription factors (NFAT, NF-κB, STAT6, and GATA3)." (PMID 37569348, 2023). "We demonstrated that PARP-1 regulates the expression of many genes whose products are crucial in asthma by controlling NF-κB nuclear trafficking and the fate of STAT6 following IL-4 or allergen exposure." (PMID 36348405, 2022). "Herein, we extensively validate this fungus-driven model with respect to established gene induction patterns in human CRS and asthma and further evaluate the central role of STAT6." (PMID 35281012, 2022). "STAT6 is activated by cytokines IL-4 and IL-13 and mediates the occurrence of allergic diseases, such as asthma, atopic dermatitis, and eosinophilic esophagitis." (PMID 35204186, 2022). "JAK-STAT6 signaling can aggravate ovalbumin-induced asthma in mice, and STAT6-/- mice are highly resistant to allergic pulmonary inflammation." (PMID 35204186, 2022). "Conversely, mice treated with Imuno TF and challenged with OVA had a significant reduction of gene expression for STAT6 (7A) compared to asthma mice." (PMID 36685604, 2022). "Activation of Fhl2 by recall allergen stimuli downregulated Bach2 and JunD and activated the ERK1/2-AP1 and STAT6 pathways, inducing a memory-driven asthma phenotype." (PMID 36524132, 2022). "IL-4 and IL-13, the cytokines upstream of STAT6, increased in human asthma, and clinical trials targeting the IL-4/IL-13/STAT6 pathway are ongoing." (PMID 35204186, 2022). "Expression levels of IL1RL1 (P = 0.0002 vs. MA, P = <0.0001 vs. SA) and STAT6 (P = 0.0079 vs. MA, P = <0.0001 vs. SA) were significantly higher in mild-moderate and severe asthma compared to controls." (PMID 35386986, 2021). "In order to assess the alleviating effect of BV on asthma, we examined the effect of BV on the phosphorylation of STAT6 in A549 cells treated with IL-13." (PMID 34822557, 2021). "The STAT1 and STAT4 pathways are considered vital for Th1 differentiation, while the IL-4/IL-13/STAT-6 pathway has been confirmed to be the major modulator of Th2 differentiation in asthma pathophysiology." (PMID 34093516, 2021).
asthma (continued). "The intraperitoneal transfer of DClps inhibited the development of Th2 allergic responses by increasing Tregs, suppressing CD4+ memory T cells and decreasing STAT6 phosphorylation level in OVA-induced asthma models." (PMID 34093516, 2021). "The binding of IL-13 to its receptor causes activation of the signal transducer and activator of transcription (STAT6), which facilitates mucus metaplasia in asthma." (PMID 34822557, 2021). "Interleukin (IL)-4/IL-13 pathway genes, including IL-4, IL-13, IL-4 receptor alpha (IL-4Ra), and signal transducer and activator of transcription 6 (STAT6), were frequently linked to serum IgE levels and asthma as they can regulate IL-4 and IL-13 cytokines." (PMID 33810791, 2021). "IL-13 binding to its receptor induces the phosphorylation of STAT6, causing AHR and mucus overproduction in asthma." (PMID 34822557, 2021). "It has been seen that in individuals suffering from asthma there is overexpression of numerous genes and proteins, such as Signal Transducer and Activator of Transcription 6 (STAT6), Plasminogen Activator Inhibitor-1 (PAI-1), and Spleen Tyrosine Kinase (Syk)." (PMID 31979001, 2020). "Low-level phosphorylated STAT6 hinders IgE class switching, inhibits IgE production, and ultimately alleviates the development of asthma." (PMID 32636842, 2020). "CLCA1 is an IL-4 and IL-13 inducible, STAT6-dependent mediator of chloride ion transport/fluid production and mucin/mucus production and is involved in asthma." (PMID 32431691, 2020). "Here, a novel protonable copolymer was realized for the production of polyplexes with a siRNA (inhibitor of STAT6 expression in asthma), with the aim of a pulmonary administration." (PMID 31979001, 2020). "In brief, these data suggest that EP4 further regulates the expression of PPARγ by activating Akt and then PPARγ participates in the down-regulation of phospho-STAT6 and IgE production, eventually attenuating the development of asthma." (PMID 32636842, 2020). "Some transcription factors (e.g., signal transducer and activator of transcription-6 [STAT-6] and activator protein 1 [AP-1]) are involved in the pathogenesis of asthma." (PMID 31500199, 2019). "Asthma-induced Brucella susceptibility appears to be dependent on CD4+ T cells, the IL-4/STAT6 signaling pathway and IL-10, and is maintained in IL-12- and IFN-γR-deficient mice." (PMID 30147700, 2018). "IL-4Rα Q576R, which can affect the binding of IL-4 and phosphorylation of intracellular substrates including signal transducer and activator of transcription 6 (STAT6), has been linked to many autoimmune disorders such as asthma, atopy, and allergy." (PMID 28511637, 2017). "According to an OVA-induced asthma model experiment using STAT6-/- mice, airway eosinophilia was blocked by reducing eotaxin level in the pulmonary tissues." (PMID 27010397, 2016). "These asthma genes were enriched for targets of STAT6 signaling and they were nested within a larger coexpression module comprising 406 genes." (PMID 26922672, 2016). "Signal transducer and activator of transcription 6 (STAT6) and nuclear factor kappa B (NF-κB) have been demonstrated to regulate many pathologic features of asthma, and both are activated by IL-4." (PMID 26075216, 2015). "We show using a specific antagonist of STAT6 activation that such toxicity can be abrogated, revealing a new approach to the management of asthma and related allergic disorders." (PMID 26605551, 2015). "IL-4 uses Janus kinases (JAKs) to initiate the signaling cascade and activate signal transducer and activator of transcription 6 (STAT6), consequently modulating allergic airway inflammation in asthma and other diseases." (PMID 26075216, 2015). "Focussing on genes of the Th2 pathway (IL4, IL4R, IL13, GATA3, STAT6), the authors demonstrated that the odds of asthma tended to decrease at the age of 10 years with increasing GATA3 methylation." (PMID 26052354, 2015).